ADM (adrenomedullin)
Diseases named in the same sentence as ADM in open-access papers (continued):
Sharing a sentence is not in itself a finding about the gene and the disease.
infectious disease (5 papers, 2008 to 2024). A disorder directly resulting from the presence and activity of a microbial, viral, or parasitic agent in humans. "These possibilities could materialize thanks to new potential treatment strategies with anti-ADM antibodies in a multitude of areas, including the cardiovascular, infectious disease, or oncology fields." (PMID 39200990, 2024). "Therefore, we believe that neopterin and pro-ADM levels were inadequate to indicate the disease severity and detection of infectious diseases." (PMID 30559815, 2018).
nephropathy (5 papers, 2010 to 2023). A nonspecific term referring to disease or damage of the kidneys. "By contrast, vasodilator peptides, such as ANP and adrenomedullin, have protective actions against tissue injuries caused by various stresses and may therefore be useful as drugs for certain cardiovascular and renal diseases." (PMID 22675352, 2012). "Plasma and urine ADM levels are known to deviate from normal levels in many renal diseases." (PMID 36010070, 2022).
heart disease (4 papers, 2011 to 2024). "Beyond its role in vasodilation, adrenomedullin has demonstrated significant cardioprotective effects, particularly in the context of heart disease." (PMID 39200990, 2024). "Presumably, ANP reflects the central volume overload and intrinsic heart disease, whereas ADM reflects the decompensated reaction to the multifactorial stress state in preserving the integrity of the cardiovascular system in ESRD." (PMID 21408188, 2011).
metabolic disease (4 papers, 2017 to 2025). A congenital disorder (due to inherited enzyme abnormality) or acquired (due to failure of a metabolically important organ) disorder resulting from an abnormal metabolic process. "Given that ADM is widely involved in the regulation of cardiovascular functions and inflammatory process, increased ADM secretion from the liver may trigger other diseases such as vascular diseases and global inflammation beyond metabolic diseases." (PMID 40788055, 2025). "In this context, we explored the levels of adrenomedullin, which is thought to bind CTRL but might also act on CTR and exert beneficial effects on HFD-induced metabolic disease." (PMID 28666011, 2017).
nervous system diseases (2 papers, 2023). "Bioactive adrenomedullin (bio-ADM) is a 52-amino acid peptide that is an important peptide hormone in nervous system diseases." (PMID 36964268, 2023). "Adrenomedullin recently been discussed as an important participant in neurological diseases, and has been seen to exhibit a neuroprotective effect against brain insults." (PMID 38201257, 2023). "Circulating biologically active adrenomedullin (bio-ADM) is a promising novel biomarker that is an important regulatory factor in nervous system diseases." (PMID 36964268, 2023).
neurodegenerative disease (2 papers, 2022 to 2025). A disorder of the central nervous system characterized by gradual and progressive loss of neural tissue and neurologic function. "In neurodegenerative diseases, ADM interacted with cytoskeletal proteins in neurons, influencing microtubule dynamics and contributing to the regulation of neuronal function." (PMID 40529377, 2025). "Furthermore, ADM had been identified as a potential therapeutic target in neurodegenerative diseases." (PMID 40529377, 2025).
brain disorder (1 paper, 2010). A disease affecting the brain or part of the brain. "On the other hand, high levels of ADM in plasma have been found in patients with chronic Schizophrenia, which confirms its role in brain disorders." (PMID 20515496, 2010).
digestive diseases (1 paper, 2025). "Notably, leptin (LEP), GDF15, and ADM showed the strongest associations with lung function, while BST2, THBS2, and CEACAM1 exhibited the most significant associations with digestive diseases." (PMID 40048323, 2025).
ADM also shares sentences with these, for which no sentence is quoted: acute myocardial infarction (5 papers); Glucose intolerance (4); clear cell renal cell carcinoma (3); dilated cardiomyopathy (3); essential hypertension (3); metabolic syndrome (3); schizophrenia (3); systemic inflammatory response syndrome (3); bronchopulmonary dysplasia (2); cardiac arrest (2); cholangiocellular carcinoma (2); chronic periodontitis (2); liver cirrhosis (2); metastatic melanoma (2); polycystic ovary syndrome (2); psoriasis (2); respiratory failure (2); respiratory infections (2); Uterine leiomyoma (2); adrenal tumours (1); allergic contact dermatitis (1); amyotrophic lateral sclerosis (1); arterial disease (1); astrocytoma (1); astroglioma (1); bacterial pneumonia (1); benign ovarian tumor (1); biliary tract cancer (1); bipolar disorder (1); cardiac amyloidosis (1).
A further 81 diseases each share a sentence with ADM in 1 paper.